CD163 (CD163 molecule)
Diseases named in the same sentence as CD163 in open-access papers (continued):
Sharing a sentence is not in itself a finding about the gene and the disease.
infection (continued). "CD163+Erg2+ M2 macrophages were reduced on day 1 post-infection in WT and Ifnlr1−/− mice but present in Ifnar1−/− mice, suggesting type I IFN drives depletion of M2 macrophages early post-infection." (PMID 38530032, 2024). "Through the integrated analysis of miRNA-mRNA expression profiles, it was found that the expression of FOXN4, MUC4, KLK1 and CD163 were up-regulated under the action of miR-106b-3p after infection." (PMID 38178220, 2024). "Cellular infection by PRRSV is dependent on the presence of its obligate receptor CD163, which under normal circumstances functions in the clearance of hemoglobin." (PMID 38389522, 2024). "So far, a collection of studies have supported the idea that CD163 is a binding receptor for some bacteria and viruses during the process of infection." (PMID 36977274, 2023). "We also examined genes for known markers of immune cells and found nociceptor-ablated mice had significantly lower expression of B cell marker, Cd19, and M2 Macrophage marker, Cd163, after 14 days of infection compared to cre-control mice." (PMID 37845223, 2023). "CD163 was expressed on some Mo and downregulated upon infection with the Velogenic strain as was the expression of CD14." (PMID 36680295, 2023). "It has been reported that during infection, CD163 triggers the production of pro-inflammatory cytokines." (PMID 37614559, 2023). "Specifically, we aimed to evaluate some polymorphic markers of the CD163 gene, informative about the degree of response to the infection, in order to define the genotypes existing in the population object of the study." (PMID 37570285, 2023). "Our results showed that the expression of CD163 was affected by both conditions (cultivation and infection)." (PMID 37258711, 2023). "Concerning the host, different genes are involved in PRRSV recognition and infection, but this investigation focuses on the CD163 gene since different studies have demonstrated, by now, its central role in viral susceptibility." (PMID 37570285, 2023). "CD163, which encodes the membrane receptor used by the PRRSV to enter macrophages and initiate infection, has been identified as one of the most promising marker genes associated with genetic susceptibility to the disease." (PMID 37570285, 2023). "Consistent with previous studies, we observed that pretreatment of MARC-145 cells with an anti-CD163 antibody completely prevents the cells from being infected with the C1 virus, clearly indicating that the virus requires CD163 for infection." (PMID 36560826, 2022). "The effects of exogenous vitamin D3 treatment on macrophage polarization markers CD80 and CD163 following infection with MAP for 24 hrs in vitro were assessed using immunocytochemistry and confocal microscopy." (PMID 36275033, 2022). "Particularly, PRRSV strains with a K160 in GP2 efficiently infect MARC-145, PK15-pCD163, and PAMs while mutants with a K160I substitution in GP2 infect MARC-145 but not PK15-pCD163 and PAMs, even though this mutant still requires CD163 for infection." (PMID 36560826, 2022). "Treatment of MDMs with 1,25(OH)2D3 and infection with MAP in vitro resulted in increased CD163 expression in JD- control (P < 0.001) and JD+ clinical cows (P < 0.001)." (PMID 36275033, 2022). ",21Lutzomyia longipalpis SGEs modulated the infection by preventing theattraction of monocytes and CD163 macrophages throughout the course of infection." (PMID 35920504, 2022). "Although the expression of porcine CD163 alone in PK-15 cells is enough to render the cells susceptible to PRRSV, the level of infection can be greatly enhanced when the cells are co-transfected with CD163 and Sn." (PMID 36560826, 2022). "CD163 is a glycoprotein expressed on the membrane of monocytes and macrophages and is an important serum marker for early infection and inflammation." (PMID 36137346, 2022).
infection (continued). "In the brain, CD163 was almost uniformly expressed by the microglia and Ly6Cint during infection, with a decrease from D7 posttreatment, while Ly6Clow monocytes exhibited very low expression levels of this receptor." (PMID 36310859, 2022). "In vivo challenge of CD163 null pigs with the Georgia 2007/1 isolate of ASFV resulted in robust infection of the pigs ruling out a significant role for CD163 in infection." (PMID 35755158, 2022). "Porcine reproductive and respiratory syndrome virus (PRRSV) has a restricted tropism for macrophages and CD163 is a key receptor for infection." (PMID 36560826, 2022). "In this study, we systematically tested the porcine CD163 stably expressing 3D4/21 cells for infections with various PRRSV strains." (PMID 36146862, 2022). "Since the C1 virus did not efficiently infect PAMs or PK15-pCD163, we sought to determine if it still required CD163 for infection." (PMID 36560826, 2022). "Negligible alterations in the expression of MHC class II DR or CD163 on either MagPam2Cys-stimulated or untreated moMΦ were observed following infection with ASFV." (PMID 36298767, 2022). "Compared with the CK group, a high CD163 expression was observed after Pm infection after 1, 2, 5 and 7 days in this study." (PMID 35739866, 2022). "The levels of sTREM-1, S CD163 and STweak in serum of patients with different infection severity and different cardiac function grades were compared among the three groups." (PMID 35480505, 2022). "In our previous study, we described a reduction of CD163 expression 21 h post-infection with 26544/OG10, and in this study we also observed this effect in MagPam2Cys-stimulated moMΦ." (PMID 36298767, 2022). "The results showed that the porcine CD163-expressing macrophages support the infections of PRRSV2 of lineages 1, 5, and 8, as evidenced by Western blotting, immunofluorescence assay, quantitative PCR, and virus titration assay." (PMID 36146862, 2022). "In summary, we systematically evaluated monoclonal porcine macrophages 3D4/21 stably expressing CD163 for infections with PRRSV of different lineages." (PMID 36146862, 2022). "The incorporation of studies using genetically modified pigs shows that CD163 is the only putative receptor that is necessary and sufficient for infection." (PMID 33916997, 2021). "Whereas in a previous study we were able to describe the replenishment of CD163+ cells in the lung of SU1-bel infected pigs about one month post infection, this phenomenon was already observed at two weeks post-infection in the present study." (PMID 33482914, 2021). "Recombinant CD163 SRCR1-4 inhibits infection of PRRSV-1 and PRRSV-2 in PAMs by competitive binding to MYH9." (PMID 33916997, 2021). "cCasp8 and to a lesser extent cCasp9 were activated by both PRRSV-1 strains after one week post-infection together with a replenishment of both CD163+ and Arg-1+ pulmonary macrophages." (PMID 33482914, 2021). "The perimeter (p = 0.0292), number of knots (p = 0.0062), sprouts (p < 0.0001), and CD163+ HCs (p < 0.0001) showed significant differences by the trimester of infection." (PMID 34177930, 2021). "By measuring changes in host proteins in concentric rings around infected hepatocytes and correlations between these proteins we identified an influx of CD163+ Kupffer cells towards the parasite during the second half of liver stage infection." (PMID 35111697, 2021). "Further analysis showed that the infection rate was proportional to the abundance of CD163 on the cell surface." (PMID 33916997, 2021). "The recovery of CD163+ macrophages at the end of the study represents an attempt to restore pulmonary macrophage subpopulations lost during the early stages of the infection but also a macrophage polarisation into M2 macrophages." (PMID 33482914, 2021). "Overexpression of ADAM17 inhibited PRRSV infection by regulating CD163 expression, whereas the reduction of ADAM17 expression by siRNA led to upregulation of CD163, which further increased infection with PRRSV." (PMID 33916997, 2021).
infection (continued). "Macrophage-specific surface receptor CD163 is required for the infection of pigs by PRRS viruses (PRRSV)." (PMID 32727587, 2020). "Previous studies revealed that CD163 mediates PRRSV uncoating instead of internalization during productive infection, which is a step after virion internalization to the host cells." (PMID 32727587, 2020). "As the upregulation of CD163 facilitates PRRSV entry, the minimized CD163 expression will further hinder the infection." (PMID 33050150, 2020). "Higher expressions of iNOS and CD163 were observed in lung lesions of CSE-exposed mice with BCG-infection, where co-localization of iNOS or CD163 with F4/80 were demonstrated, suggesting presence of M1 and M2 polarized macrophages in lung lesions." (PMID 32973788, 2020). "During infection, PRRSV replicates in the CD163+ cells in the lungs and induces apoptosis at the early stages of infection." (PMID 32404209, 2020). "We first detected the mRNA expression of CD163 at different time points of infection and found that CD163 expression gradually rose to the highest at 24 hpi and then fell." (PMID 32269560, 2020). "Further studies showed that the SRCR5 domain of the CD163 extracellular region plays a key role in PRRSV infection, and pig deleted SRCR5 of CD163 can fully resist the infection of PRRSV." (PMID 33251273, 2020). "Alveolar macrophages (AMs) are the target cells of PRRSV, CD163 on porcine AM membranes has been revealed as an essential receptor mediating infection of PRRSV." (PMID 33251273, 2020). "Due to the enhanced cytokine expression, a disintegrin and metalloproteinase 17 was activated to promote the cleavage of membrane CD163, which resulted in suppression of infection." (PMID 32401783, 2020). "CD163 is involved in the clearance of Hb:Hp complexes, serum levels of which are elevated after birth, infection, trauma, and organ damage." (PMID 31953452, 2020). "We do not have a proper explanation for the increased expression of CD163 mRNA over the course of infection in SRCR5-edited PAMs." (PMID 31440241, 2019). "For these experiments, both CD163 KO and WT pigs were comingled after infection, which allowed for the continuous exposure of the CD163 KO pigs to virus shed by the infected WT pigs." (PMID 30658381, 2019). "Next, PAMs isolated from both edited and WT pigs were infected with the JXA1 strain, then CD163 mRNA expression was analyzed at 12, 24, 36, 48, and 60 h post infection (hpi)." (PMID 31440241, 2019). "Infection of pBMDMs with Kp52145 resulted in a significant upregulation of the surface expression of the M2 marker CD163 as detected by flow cytometry." (PMID 31796543, 2019). "For example, the removal of the N184 glycosylation site, which blocked infection, retained the ability to interact with CD163." (PMID 30658381, 2019). "In our analysis, standard correlation analysis identified the frequency of CD163+ monocytes at baseline and the frequency of TNFa+ monocytes at 3 weeks post-infection only as statistical correlates of TB pathology." (PMID 31736945, 2019). "This study, together with most recent ones, questioned the notion of CD163 relevance during the infection." (PMID 30862035, 2019). "Prior infection moDC showed high expression levels of CD163 and low CD169 and replication was clearly restricted to a CD163+ CD169dim phenotype." (PMID 30862035, 2019). "The rate of weight gain of CD163 SRCR5-edited piglets was significantly higher than that of WT controls after day 7 post infection." (PMID 31440241, 2019). "The first CD163 knockout pigs were born in 2016 and are resistant to the infection of species 2 PRRSV isolate." (PMID 31440241, 2019). "In a subsequent study, macrophages from CD163 KO pigs were shown to be resistant to infection with PRRSV-1 and PRRSV-2." (PMID 30658381, 2019). "Surprisingly, although the small deletion of CD163 SRCR5 blocks the infection by PRRSV, we found that SRCR5-edited PAMs present a similar cytokine response to PRRSV challenge to the WT PAMs." (PMID 31440241, 2019).
infection (continued). "Pretreatment of PAMs with tetradecanoyl phorbol acetate (TPA) or lipopolysaccharide (LPS) shows that the CD163 expression decreases, and accordingly infection of PRRSV is reduced." (PMID 29682543, 2018). "We demonstrated that the CD163 expression level in a target cell must reach or exceed an infection initiated threshold for PRRSV to establish a successful infection." (PMID 29552301, 2018). "A functional CD163 protein is required for infection by porcine reproductive and respiratory syndrome virus, which is a serious pathogen with major impacts on pig production." (PMID 30572815, 2018). "We further analyzed the infection ratios of these different cells by flow cytometry and found that the number of infected cells increased with increasing CD163 abundance; the same conclusion was reached at the viral protein level." (PMID 29552301, 2018). "All of these data demonstrate that CD163 plays an important role in determining PRRSV susceptibility and productive infection." (PMID 29682543, 2018). "The L1 is used to indicate inflammatory processes, originating in the initial period of infection and CD163 is present in different populations of macrophages related to processes of tissue repair." (PMID 29896161, 2018). "Transmembrane anchoring and interaction with SRCR domain 5 (SRCR5) of CD163 were found to be essential for successful infection with PRRSV." (PMID 29925651, 2018). "We used CD 163-negative cells isolated from PAM-Tang-high cells by flow cytometry to perform an infection assay, and the results demonstrated that CD163 depletion in PAM-Tang-high is sufficient to block PRRSV replication." (PMID 29552301, 2018). "Groundbreaking work with porcine reproductive and respiratory syndrome virus (PRRSV) has shown that gene editing of a critical entry factor (CD163) confers complete resistance to infection in pigs." (PMID 30881690, 2018). "CD163 is involved in the cytokine response to infection and immune stimuli as well as hemoglobin-haptoglobin (Hb-Hp) uptake." (PMID 29925651, 2018). "Porcine sialoadhesin (pSn, Siglec-1) and CD163 are main entry mediators facilitating infection of porcine macrophages by PRRSV." (PMID 30021620, 2018). "A functional CD163 protein is required for infection by porcine reproductive and respiratory syndrome virus (PRRSV), which is a serious pathogen with major impacts on pig production." (PMID 30572815, 2018). "Successful infection of porcine macrophages and monocytes by ASFV correlates to the expression of the CD163 scavenger receptor, a hallmark of macrophage maturation." (PMID 28489063, 2017). "Taken together, our in vitro infection data suggest that both macrophages and neutrophils are sources of sCD163 during Leishmania infection and that the quantity of CD163 is directly correlated with infection level." (PMID 28355218, 2017). "The transmembrane anchoring and an interaction with the SRCR domain 5 (SRCR5) of CD163 were found to be essential for successful infection with PRRSV." (PMID 28231264, 2017). "Porcine reproductive and respiratory syndrome virus (PRRSV) exhibits a highly restricted tropism for cells of the monocyte-macrophage lineage, utilizing porcine CD163 (pCD163) as an indispensable cellular receptor for infection." (PMID 29121904, 2017). "CD163+ cells showed higher infection (MFI = 913.167) than CD40+CD163- (MFI = 715.143) cells (p = 0.0044, Friedman paired test)." (PMID 28355218, 2017). "Only 3 genes each in the spleen (B2m, Lst1 and Edf1) and the brain (Six6, Cd163 and Bmp10) were modulated at all three time points after V3034 infection." (PMID 28446152, 2017). "In this study, CD163-positive fetuses, recovered between 109 days of gestation or 20 days after maternal infection, were completely protected from PRRSV in dams possessing a complete knockout of the CD163 receptor." (PMID 29042674, 2017).
infection (continued). "In mice, the expression of the haptoglobin receptor (Cd163) on macrophages declines dramatically after infection with T. congolense and is the earliest indicator of infection." (PMID 29077717, 2017). "All three virus subtypes resulted in infection levels of 40–60% in wild type and heterozygous animals, with more than 98% of infected cells being classified as CD163 positive." (PMID 28231264, 2017). "We observed that infection by Leishmania induced CD163 expression on the surface of both macrophages and neutrophils, identifying these cells as potential sources of the sCD163 detected in serum." (PMID 28355218, 2017). "To assess the impact of infection on CD163 we infected cells in vitro with various Leishmania species." (PMID 28355218, 2017). "Understanding how PRRSV surface glycoproteins interact with CD163 should lead to the identification of conserved epitopes which are necessary for infection." (PMID 28608816, 2017). "The identification of CD163 as the necessary and sufficient receptor for infection supports the implications of broadly neutralizing antibodies that a conserved target is present on all PRRSV." (PMID 28608816, 2017). "Collectively, our data indicate the induction of CD163 expression during infection with M. leprae and Leishmania species, likely modulating the immune response to permit high levels of infection and the most severe clinical presentations of these diseases." (PMID 28355218, 2017). "pSn and CD163 have been identified as the mostimportant host receptors that facilitate the infection of PRRSV into alveolarmacrophages." (PMID 28742001, 2017). "Our observations stand in apparent conflict with evidence from static gain of function experiments that CD163 is essential for productive infection of PAMs with PRRSV." (PMID 27770812, 2016). "Previous evidence suggests that the scavenger receptor CD163 is essential for productive infection of PAMs with PRRSV." (PMID 27770812, 2016). "The significant infection group × day interaction in the statistical models for CD163 kinetics indicates different kinetic trends in these biomarkers between PRRSV- and mock infected samples." (PMID 27770812, 2016). "Alveolar macrophages recovered after the 2 h infection, showed increased expression level of CD163, SLAI and SLAII when compared to the macrophages recovered from the non-infected pig." (PMID 26395877, 2015). "For CD163 and CD169, which are involved in PRRSV-entry into host cells, our results show that prior to infection porcine moDCs express high levels of CD163 but only very low levels for CD169." (PMID 25990845, 2015). "CD163 is a macrophage receptor for the bacterial binding and can induce the pro-inflammatory cytokines during infection." (PMID 25906258, 2015). "For ASFV, the role of CD163 is to act as a point of attachment for subsequent macrophage internalization leading to infection of the monocyte/macrophage, an interaction that can be inhibited by a specific CD163 monoclonal antibody." (PMID 26111002, 2015). "This is supported by the fact that virus replication in endometrium and placenta precedes fetal infection and that the number of sialoadhesin positive (Sn+)/CD163+ macrophages in endometrium and placenta plays a role in fetal death." (PMID 25275491, 2014). "There was no statistical difference in the percentage of cells which expressed VP30 following infection with the field isolates between the parental cells and cells expressing exogenous CD163." (PMID 24398227, 2014). "It was also demonstrated in the present study that “inflammatory” CD163+ monocytes appeared in the lung tissue after APP-infection." (PMID 24134635, 2013). "In Lena-infected nasal mucosa, CD163+Sn+, CD163+Sn- and to a lesser extent CD163-Sn- monocytic subtypes were involved in infection." (PMID 24007551, 2013). "In the results, it was shown that infection seems to start from CD163+Sn+ cells and in Lena strain it spreads later to other cell types." (PMID 24007551, 2013).